CD4 (CD4 molecule)
Diseases named in the same sentence as CD4 in open-access papers (continued):
Sharing a sentence is not in itself a finding about the gene and the disease.
tumor (continued). "Genetically engineered mice deficient for CD8+ cytotoxic T-lymphocyte (CTLs), CD4+ Th1 helper T-cells, or natural killer (NK) cells components of the immune system, show an increased tumor incidence." (PMID 34771694, 2021). "Tumor-associated macrophages stimulate the generation of induced Tregs (regulatory T cells) from CD4+ T cells." (PMID 33980865, 2021). "When CD4 and antigen-presenting cells count decrease meaningfully, skin becomes susceptible to numerous opportunistic infections and neoplastic diseases." (PMID 34422644, 2021). "Expansion and persistence of CD4+ T cells directed against another tumor-specific mutation (BRAF) has also been observed in another patient who achieved long-term tumor control after TIL transfer." (PMID 33546283, 2021). "We found that CCT6A levels correlated negatively with levels of infiltrating B cells, CD4+T cells, neutrophils, and dendritic cells but positively associated with tumor purity, suggesting a potentially immune-suppressed role of CCT6A." (PMID 34017352, 2021). "To better characterize the T cell phenotype of CD4 + immune cells that are associated with outcome in FL, we performed CyTOF on viable, cryopreserved, single-cell suspensions from tumor biopsies of 51 newly diagnosed FL patients from our cohort." (PMID 34267181, 2021). "Tumor cells and other cellular components of the tumor microenvironment, such as cancer associated fibroblasts, CD4+ T cells and myeloid cells, are linked by a web of interactions." (PMID 34290984, 2021). "Using a Spearman rank correlation, we found a significant correlation whereby a reduction of CD3 + (p = 0.04, rho = 0.60) and CD4 + (p = 0.01, rho = 0.72) T-cells was associated with decreased residual tumour content post-1 cycle of treatment." (PMID 33983492, 2021). "In CCA, CD8+ and CD4+ cytotoxic T lymphocytes have been investigated with regard to their presence, locations within the tumor, and association with patients’ survival." (PMID 33579265, 2021). "In this study, it was observed that the combined treatment causes an accumulation of CD4+ T cells in the tumor compared to the administration of the vaccine only." (PMID 33902630, 2021). "Specifically, PI3Kγ contributes to the differentiation and migration of key support cells in the tumor microenvironment, such as CD4+ T cells and M2 tumor-associated macrophages, which sustain leukemia cells in a protective niche." (PMID 33805745, 2021). "Preclinical evidence showed that PI3Kδ inhibition directly affects the leukemic B cells, whereas PI3Kγ inhibition targets key support cells in the tumor protective niche, such as CD4+ T cells and M2 tumor-associated macrophages." (PMID 33805745, 2021). "MAF was significantly associated with CD4 + T cells (r= 0.129, P= 3.20e−02) and dendritic cells (r = 0.283, P= 1.75e−06), and negatively correlated with tumor purity (r = −0.146, P = 1.45e−02)." (PMID 34784845, 2021). "ESR1 expression level was negatively associated with tumor purity (r= – 0.141, P= 1.88e−02), B cells (r = 0.141, P= 1.81e−02), CD4 + T cells (r = 0.185, P= 2.03e−03), and macrophages (r = 0.143, P = 1.76e−02)." (PMID 34784845, 2021). "Administration of FAK inhibitors or FAK-specific depletion in cancer cells caused tumour regression with increased CD4+ and CD8+ T cell infiltration and decreased Tregs in vivo." (PMID 33573141, 2021). "There are studies that claim that tumor eradication is associated with a low number of CD4+ T lymphocytes and studies that claim that an increased percentage of CD4+ T lymphocytes are associated with the response to treatment and eradication of the tumor." (PMID 34054956, 2021). "TIMER database analysis showed that ACSS2 expression in CESC was associated with tumor infiltration of B cells, CD4+ and CD8+ T cells, and cancer-associated fibroblasts (CAF)." (PMID 34206705, 2021). "And the tumor promotion associated immune cells, including Macrophages M2, CD4 memory resting T cells, and Macrophages M0, were more abundant in HPV− HNSC." (PMID 34530752, 2021).
tumor (continued). "Overall, we demonstrate that TEG011 equipped with human CD8α coreceptor elicits superior tumor control and long-term persistence, which mainly impacted numbers of γδTCR+CD4+CD8+ double-positive TEG011_CD8α cells, and associated with better T-cell infiltration." (PMID 34759930, 2021). "Meanwhile, COL1A1 expression exhibited a significant association with tumor purity, CD4 T cells, macrophages, and neutrophils." (PMID 33490271, 2021). "Prior work has demonstrated that the treatment with recombinant human TNF-α in a B16F10 melanoma mouse model of lung metastasis increased tumor burden and metastatic foci and was associated with increased numbers of pulmonary regulatory CD4+/Foxp3+ T cells." (PMID 33986746, 2021). "Lower CCT6A expression was associated with higher infiltrating B cells, CD4+ T cells, neutrophils, and dendritic cells, but positively correlated with tumor purity." (PMID 34017352, 2021). "High risk score was positively associated with tumor infiltrating immune cells including CD4+ T cells, neutrophils, and activated NK cells, and negatively associated with hematopoietic stem cells, myeloid dendritic cells, and uncharacterized cells." (PMID 34660608, 2021). "CD4+ T cells most commonly associated with anti-tumor responses include Th1, Th9, and Th17 cells, which drive cell-mediated responses, while Th2 cells support the humoral arm of the adaptive immune response considered less effective at containing tumors." (PMID 33669271, 2021). "On the other hand, CD4 Th1 cells have an indirect effect on the polarization of tumor-associated macrophages (TAMs) towards a proinflammatory phenotype through the secretion of cytokines such as interferon (IFN)-γ and IL-1." (PMID 34830805, 2021). "In the glucose-deficient TME, its key participants involved in anti-tumor immune regulation, CD4+TILs, CD8+TILs, MDSCs, M1/M2 TAMs, Tregs and other immune cells, are dysfunctional due to metabolic reprogramming." (PMID 34858835, 2021). "In turn, this underlined the in vitro survival of CD4+ subsets of activated tumor-derived Jurkat T cells and their proinflammatory secretion during 14-day contact with rough CaP coating bearing a negative sign of ZP." (PMID 34279263, 2021). "The two immune cell subsets that can principally control MHC-I null tumor variants, are natural killer (NK) cells and CD4 T cells." (PMID 34201655, 2021). "The high level of expression of Treg cells is associated with suppression of the anti-CRC tumor immune response driven by CD4 T cells." (PMID 34163519, 2021). "There, APC presents the tumor neoantigen to the naïve T cells, which causes them to transform into effector T cells, CD4+ or CD8+ lymphocytes." (PMID 34356899, 2021). "The traditional concept is that CXCL10/CXCL9 largely produced at the tumor site is associated with directing the migration of CXCR3+ effector CD4+ and mostly effector -cytotoxic CD8+ T cells, and CXCR3+ NK cells to the tumor site." (PMID 34944943, 2021). "This beneficial effect was associated with increased numbers of tumor-infiltrating CD4+ and CD8+ T cells concomitantly with reduced percentages of regulatory T cells." (PMID 33920884, 2021). "The main adaptive immune response to kill tumor cells begins with recognizing tumor antigen via antigen-presenting cells (APCs), which further present tumor-associated antigens by MHC II molecules to the T cell receptors (TCRs) of CD4 helper T (Th) cells." (PMID 33413697, 2021). "Individuals hospitalised for digestive, infectious diseases or neoplasms had lower median CD4 counts compared to other causes." (PMID 33926373, 2021). "B cells in these structures can recognize tumor-associated antigens, so it is reasonable to infer that there are CD4 T cells with similar specificities in the lymphoid structures." (PMID 33968757, 2021).
tumor (continued). "The results showed that ABCC5 expression is significantly associated with the infiltration of B cells, CD4+ T cells, macrophages, neutrophils, and dendritic cells in the tumor microenvironment." (PMID 33994848, 2021). "The amount of immune cell infiltration in low-risk patients was significantly higher than that in high-risk patients, and included cell types such as B cells, CD4+ T cells, macrophages, Th cells, and tumor-infiltrating lymphocytes (TILs)." (PMID 33929972, 2021). "Seven days after PT, significant infiltration of CD8+ T cells, CD4+ T cells and type 1 tumor associated-macrophage (TAM1) was observed." (PMID 34188135, 2021). "The low expression of IL17A caused by the Smad7 expression in tumor-infiltrating CD4(+) T cells enabled the TNF-α-mediated killing of cancer cells both in vitro and in vivo." (PMID 34059951, 2021). "A very heterogenous immune infiltrate has been described in MPM with a predominant role for tumor-associated macrophages (TAM) and tumor-infiltrating CD4+ and CD8+ T lymphocytes." (PMID 34199544, 2021). "The methylation changes were associated with transcriptomic changes for 341 genes in CD4+ tumor infiltrating T cells compared to blood." (PMID 34262562, 2021). "Expression of GGT1 was negatively correlated with tumor purity (r = −0.236, P = 9.03e-6) and positively associated with infiltration of CD4+ T cells (r = 0.148, P = 6.11e-3), macrophages (r = 0.163, P = 2.54e-3), and dendritic cells (r = 0.116, P = 3.25e-2)." (PMID 34513707, 2021). "Linear correlation analysis showed that higher level of serum CA153 was associated with higher density of CD3+ or CD4+ TILs in the tumor microenvironment with a coefficient of 0.168 (p = 0.019) and 0.207 (p = 0.004), respectively." (PMID 33718143, 2021). "As to the discrepancy of immune cell infiltration, patients with low m6Ascore had an elevation of Tregs and CD8+T cells but a low level of resting memory CD4+T cells, indicating an association between m6A modification and tumor immunity of PAAD." (PMID 34332578, 2021). "The observed alterations of these pathways in tumor associated CD4+ T cells suggested the functional significance of these pathways in the CD4+ T cells differentiation and function." (PMID 34012510, 2021). "High peripheral ImmunoCRIT was significantly associated with higher CD3+ and CD4+ cell counts within the central tumor area." (PMID 34086741, 2021). "CD4+ T cells, tumor-associated macrophages (TAMs), and tumor-associated neutrophils (TANs) act flexibly in HCC, depending on the release of different cytokines and chemokines." (PMID 33878734, 2021). "In contrast to M1 macrophages, CTLs and NK cells, immunosuppressive CD4+FoxP3+Tregulatory cells (Tregs), tumor-associated M2 macrophages, N2 neutrophils and myeloid-derived suppressor cells (MDSCs) promote tumor growth and progression." (PMID 34830312, 2021). "Ptch1-mutated SHH tumors in mice were associated with higher overall numbers of immune cells, such as myeloid derived suppressor cells (MDSCs), tumor-associated macrophages (TAMs), DCs, and infiltrating CD4+ and CD8+ T-cells, compared to NSC-mutated G3 tumors." (PMID 34771550, 2021). "Such loss of CD4 T cells was observed in both tumor-free and tumor-bearing environments, suggesting a tumor-independent regulation of intrahepatic T cells promoted by fatty liver." (PMID 34777255, 2021). "Most non-synonymous cancer mutations were immunogenic and were recognized by CD4+ helper T lymphocytes, resulting in tumor growth control." (PMID 34885150, 2021). "Differentiated, functional T-reg cells have cell surface receptors CD4 and FoxP3 among others and are associated with suppressed anti-tumor immunity." (PMID 33615011, 2021).
tumor (continued). "TLS density is associated with higher numbers of CD8+ and CD4+ T-cells in tumors, and evidence indicates that TLSs play a major role in controlling tumor invasion and metastasis." (PMID 32276524, 2020). "For example, the tumor immune microenvironment of CSCs consistently infiltrates several natural killer cells (NKs), cytotoxic CD8+ T cells (CD8+ T), CD4+ T helper cells (CD4+ T), tumor-associated macrophages, and tumor-associated neutrophils." (PMID 33362856, 2020). "The DC maturation obtained upon exposure to DAMPs and antigens released upon OR141-induced ICD is further associated with a strong tumor-specific TH1 CD4+ response and the increased migratory potential of DCs towards the lymph nodes." (PMID 32120810, 2020). "Immune cells including dendritic cell (DC), NK cell, myeloid-derived suppressor cell (MDSC), CD8+ T cell, CD4 +T cell, regulatory T cell (Treg), T helper cell 1 (Th1), T helper cell 2 (Th2), T helper cell 17 (Th17), and tumor-associated macrophages (TAMs)." (PMID 33614486, 2020). "Critically, Tbx21−/− mice depleted of CD8+ T cell were still able to promote tumor regression in 50% of the cases, whereas CD4 depletion resulted in complete loss of tumor control." (PMID 31924474, 2020). "Detection of neoantigen-specific CD8+ and CD4+ lymphocytes from peripheral blood has been subsequently described in patients with relatively low tumor mutation burden, such as ovarian and gastrointesinal cancers." (PMID 32695101, 2020). "Anti-tumor immunity is also associated with the suppression of various subsets of CD4+ regulatory T cells." (PMID 33276524, 2020). "Tumour-infiltrating CD4+ and CD8+ T cells have been reported to be associated with increased IFN-γ and TNF-α synthesis inducing tumour-specific T cell response." (PMID 32541941, 2020). "For example, after neoadjuvant chemotherapy, higher levels of epithelial lymphocytes (CD3+CD4+) and epithelial and stromal tumor‐associated macrophages (CD68+) were associated with better outcome in patients with NSCLC." (PMID 33072322, 2020). "Several studies have found that activated CD4+ T or CD8+ T tumour infiltrating lymphocytes are associated with good overall survival in HGSOC." (PMID 32937961, 2020). "Specifically, cytotoxic T cell activity is increased, whereas the levels of CD4+ T cells, MDSCs, and tumor-associated macrophages are decreased in IL-31-expressing tumors." (PMID 32843492, 2020). "Treatment with Alemtuzumab, which recognizes CD52 on CAR T cells, would eliminate infused CD4 CAR T cells after tumor depletion, thus preventing toxicities associated with CD4+ cell aplasia caused by long-term persistence of CAR T cells." (PMID 33081391, 2020). "Studies to date generally agree that CD8+ cytotoxic T lymphocytes (CTLs) and CD4+ Th1 cells are involved in effective anti-tumor immunity while FOXP3+ regulatory T cells are associated with suppression of anti-tumor immunity." (PMID 32216826, 2020). "CD8+ T cell-mediated cytotoxic effect can promote the growth of endogenous CD8+ and CD4+ T cells and immunity-associated cells, thus facilitating their antitumor function in the tumor microenvironment." (PMID 33042828, 2020). "Specifically, the contents of B cells and CD4 T cells in tumor tissues decreased with the rise of the risk score." (PMID 32695805, 2020). "In our study, we found that the levels of tumor-infiltrating CD4 T lymphocytes were negatively associated with the levels of NNT-AS1." (PMID 33426064, 2020). "Dormant tumor cells were characterized as neu expressing Ki67− and Ki67low fractions associated with the induction of local immune responses predominated by CD4+ and CD8+ T effector cell subsets." (PMID 33115528, 2020). "Addition of anti‐CTLA‐4 antibodies to ILP‐TNF/Mel/SM led to a significant increase of T helper cells and also caused a reduction of intra‐tumoural CD3+CD4+Foxp3+ regulatory T cells." (PMID 32419365, 2020).
tumor (continued). "Second, it was also found that CTX + CD4 AT greatly destroyed the multiple metabolic ways of the tumor, and thus caused the generation deficiency of GSH, the main antioxidant inside cell." (PMID 35492191, 2020). "The increased CD4+CD57+ T cells in peripheral blood lymphocytes were associated with tumor progression and had a significant inverse correlation with IFN-γ-producing capability." (PMID 32547550, 2020). "We found that PD-L1 expression was detected in 33.33% (27/81) of all the patients, mostly exhibiting a stroma-only pattern and that it was positively associated with tumor-infiltrating immune cells (CD4+, CD8+, and CD163+)." (PMID 33457428, 2020). "The tumor-associated T helper (TH) cells (CD3+ CD4+ FoxP3−) are central in augmenting an optimal adaptive anticancer response and a significant increase in PCL8-U75 L-OHP liposome–treated tumors compared to all other treatments." (PMID 32917608, 2020). "The tumor‐associated CD4/CD8 double‐positive T (DPT) cells are found enriched in L regions with synergetic expression of PD‐1/HLA‐DR/ICOS/CD45RO and exhibit a higher level of IFN‐γ, TNF‐α, and PD‐1 upon stimulation." (PMID 32670760, 2020). "G-CSF increases tumor-associated neutrophils and decreases CD4+ and CD8+ T cells in the tumor microenvironment." (PMID 32000802, 2020). "Studies have reported that CD4+ T cells inhibit tumor growth by secreting cytokines, and tumor-infiltrating CD4+ T cells are associated with increased overall survival of CCA patients." (PMID 33216732, 2020). "In cancer patients, CD4 T cells recognize unmutated self-tumor antigens, viral antigens causative of tumor transformation, and mutant peptides (neoantigens) resulting from non-synonymous mutations or gene fusion in the cancer genome." (PMID 32630460, 2020). "Presence of local tumor dormancy or distant tumor dormancy was associated with the predominance of infiltrating CD4+ and CD8+ Te or Tem subsets." (PMID 33115528, 2020). "These IL-23-producing cells and IL-17 producing cells were, at least in part, CD163 + tumor-associated macrophages (TAMs) and CD4 + IL-17 + Th17 cells, respectively." (PMID 33178182, 2020). "Using the G12D KRAS mutations as neoantigens, we found that vaccination of mice with naked synthetic peptides harboring the G12D mutation with CpG adjuvant stimulated mainly CD4+ T cell responses with limited tumor growth inhibition." (PMID 33298945, 2020). "We evaluated the disparity between primary tumor and liver metastasis in PD-L1 expression, CD4 and CD8 density and analyzed the factors associated with obvious PD-L1 disparity." (PMID 33308232, 2020). "Of note, recently it has been found that the kynurenine pathway also contributes to tumor-associated CD4+ T cell exhaustion." (PMID 33086598, 2020). "Although at low precursor frequency CD4 T cells specific for a tumor-associated self-Ag underwent robust proliferation, they acquired an irreversible exhausted phenotype." (PMID 32973794, 2020). "We observed the High‐High group was associated with PDL1 up‐regulation in the tumor, Tbet+ CD4+ T cells circulating in the peripheral blood and a gene signature characterised by a robust IFN‐γ response, antigen processing and presentation via MHC‐I pathways." (PMID 32377339, 2020). "PD-L1 is also involved in the maintenance and induction of tumor-associated Tregs by inhibiting the Akt/mTOR signaling cascade, which promotes differentiation and switch from naive CD4+ TL to induced CD4+ CD25+ FOXP3+ Tregs." (PMID 33381116, 2020). "It seemed that both FOXP3 and CD4 were associated with tumor progression, but FOXP3 was a stronger indicator." (PMID 32222891, 2020). "Blocking T cell activation can be achieved by the ability of TGF-β2 to supress HLA-DR antigen expression which is essential for tumor associated antigen presentation to CD4+ T-cells." (PMID 32765498, 2020).